GNAI1 (G protein subunit alpha i1)
Diseases named in the same sentence as GNAI1 in open-access papers (continued):
Sharing a sentence is not in itself a finding about the gene and the disease.
osteosarcoma (1 paper, 2020). A usually aggressive malignant bone-forming mesenchymal neoplasm, predominantly affecting adolescents and young adults. "The results demonstrated that gene changes of CXCL10 (P = 0.044), GNAI1 (P = 0.048), MYC (P = 0.011), and OAS1 (P = 0.0091) were significantly correlated with the overall survival of osteosarcoma patients." (PMID 32974202, 2020).
pilocytic astrocytoma (1 paper, 2020). Pilocytic astrocytoma is a rare subtype of low-grade glioma of the central nervous system characterized by a well circumscribed, often cystic, brain tumor with a discrete mural nodule and long, hair-like projections that extend from the neoplastic astrocytes. "It is nevertheless important to note that the presented BRAF multiplexed assay is not designed to detect other rare fusions involving BRAF that have been reported in pilocytic astrocytomas including FAM131:BRAF, RNF130:BRAF, CLCN6:BRAF, MKRN1:BRAF, GNAI1:BRAF, and GTF2I:BRAF." (PMID 33282733, 2020).
prostate carcinoma (1 paper, 2024). A carcinoma that arises from epithelial cells of the prostate gland. "Using these similarities, we discovered that NPBWR1 was highly similar to two other proteins in the network, GNAI1 involved in prostate cancer growth and GNAI2 involved in prostate cancer cell migration and invasion." (PMID 38983753, 2024). "Indeed, NPBWR1 shares 96 % percent of its protein partners with both GNAI1 and GNAI2 (26 out of 27 protein interactions), revealing that they might act on similar molecular pathways within prostate cancer." (PMID 38983753, 2024).
pulmonary fibrosis (1 paper, 2024). Chronic progressive interstitial lung disorder characterized by the replacement of the lung tissue by connective tissue, leading to progressive dyspnea, respiratory failure, or right heart failure. "GNAI1 was found to be under-expressed in IPF fibroblasts in the meta-analysis and has been observed in a murine model of pulmonary fibrosis." (PMID 38668384, 2024).
sarcoma (1 paper, 2023). A usually aggressive malignant neoplasm of the soft tissue or bone. "The results demonstrated that GNAI1 was not significantly or differentially expressed in normal or tumor tissues, whereas GNAI2 expression was higher in GBM and sarcomas." (PMID 37894479, 2023).
somatotropinoma (1 paper, 2014). "Here we sequenced all the coding exons of GNAI1,GNAI2 and GNAI3 in a set of young sporadic somatotropinoma patients and familial index cases, thus in patients with a disease phenotype similar to that observed in AIP mutation carriers." (PMID 25291362, 2014). "Here, we have analyzed the coding regions of GNAI1,GNAI2, and GNAI3 in a set of young sporadic somatotropinoma patients (n = 32; mean age of diagnosis 32 years) and familial index cases (n = 14), thus in patients with a disease phenotype similar to that observed in AIP mutation carriers." (PMID 25291362, 2014).
Stroke (1 paper, 2019). Sudden impairment of blood flow to a part of the brain due to occlusion or rupture of an artery to the brain.
type 2 diabetes (1 paper, 2021). "GNAI1, the top hub target, is one of the crucial genes for type 2 diabetes." (PMID 34361788, 2021).
infection (22 papers, 2011 to 2025). The state of being infected such as from the introduction of a foreign agent such as serum, vaccine, antigenic substance or organism. "The study also documented upregulation of the Gnai1 gene after infection, with an elevation of about 3.99-fold compared to the control group (1.00-fold)." (PMID 40260212, 2025). "In this study, the G-proteins inhibitory α subunits represented by Gnai1 were overexpressed at 9 days post-infection (p.i.)in the brain of infected mice." (PMID 40260212, 2025). "Huh-7 and SNU-387 cells stably expressing GNAI1 were established by the infection of lentivirus transducing unit containing GNAI1." (PMID 23691483, 2012). "Moreover, GNAI1 was found as enriched in four pathways in human macrophages following infection by Leishmania." (PMID 34992636, 2021).
tumor (20 papers, 2012 to 2025). "This study reveals the tumor-suppressive function of GNAI1, GNAI2, and GNAI3 in COAD through genetic, epigenetic, and miRNA-mediated regulation." (PMID 40819057, 2025). "Together, these alterations promote tumorigenesis and malignant transformation, underscoring the tumor-suppressive role of GNAI1/2/3 in COAD." (PMID 40819057, 2025). "Contemporarily, the protein levels of CALCRL and GNAI1 were also higher in innate resistant cells and mice tumor." (PMID 36081671, 2022). "The genes most differentially expressed in the analysis of cell lines were the same genes as the ones with strong expression differences between Wnt‐high and Wnt‐low tumor samples, namely GNAI1, NKD1, and TCF7." (PMID 35904277, 2022). "GNAI1 is known to be a suppressor of tumor cell migration and invasion that is post-transcriptionally targeted by mir-320a/c/d." (PMID 31739607, 2019). "GNAI1, another member of the subfamily, has also been shown to possess tumor-suppressive functions." (PMID 40819057, 2025). "On the other hand, we found that the chymotryptic serine proteinase Cma1, the endogenous opioid polypeptide hormone Penk, Guanine nucleotide-binding protein Gnai1 and the chemokine receptor Ccr3 were among the most down-regulated genes in SSMs after the influence of a local tumor mass." (PMID 34168645, 2021). "Overexpression of GNAI1 and GNAI2 significantly suppressed proliferation, colony formation, and migration in COAD cells, confirming their anti-tumor roles." (PMID 40819057, 2025). "The G protein subunit alpha i1 (GNAI1) acts as a suppressor of adenylate cyclase, thereby regulating cAMP levels and exerting a significant influence on tumor progression across various cancer types." (PMID 39695099, 2024). "This study was designed based on the hypothesis that members of the GNAI gene family (GNAI1, GNAI2, and GNAI3) play tumor-suppressive roles in COAD and that their downregulation may have diagnostic, prognostic, and therapeutic significance." (PMID 40819057, 2025). "Among all family members, GNAI2 and GNAI3 demonstrated differential expression levels between the GBM tumor and normal tissue samples, whereas GNAI1 was not significantly or differently expressed." (PMID 37894479, 2023). "This study demonstrates that GNAI1, GNAI2, and GNAI3 may act as tumor suppressors in COAD." (PMID 40819057, 2025). "Therefore, GNAI1 and PCAM1 might be potential tumor suppressor in LGG." (PMID 34659218, 2021).
cancer (11 papers, 2012 to 2026). A tumor composed of atypical neoplastic, often pleomorphic cells that invade other tissues. "In this study, we have demonstrated that exosomal miR-320d promotes cancer cell metastasis and enhances angiogenesis by downregulating GNAI1 expression and enhancing JAK2/STAT3." (PMID 39695099, 2024). "The pan-cancer analysis revealed the expressions of GNAI1–3 in 20 different cancer types from the UALCAN database." (PMID 37894479, 2023). "Some of the differentially expressed genes included cancer progression factors, such as Tff1 (trefoil factor 1), Anxa10 (annexin a10), Gnai1 (G protein subunit alpha i1), Areg (amphiregulin), and Mmp7 (matrix metalloproteinase 7)." (PMID 35703180, 2022). "It is worth to exploring the potential of the newly identified miR-320a/c/d-GNAI1 axis in the future anti-cancer therapy." (PMID 23691483, 2012). "Our present findings uncover a new function of GNAI1 in cancer and extend the repertoire of the GNAI family." (PMID 23691483, 2012). "The regulation of GNAI1 expression in cancer is rarely studied." (PMID 23691483, 2012). "This study is the first to investigate the role of GNAI1 in cancer." (PMID 23691483, 2012). "Furthermore, based on our in silico drug sensitivity analyses and prior reports linking GNAI2 to drug resistance in other cancers, we speculate that GNAI1 and GNAI2 overexpression could enhance chemosensitivity in COAD cells, possibly by interfering with pro-survival pathways such as PI3K/AKT." (PMID 40819057, 2025). "However, despite the physiological importance of GNAI1, its role in cancer remains unclear." (PMID 23691483, 2012).
neurodevelopmental disorder (4 papers, 2022 to 2025). A behavioral and cognitive disorder with onset during the developmental period that involves impaired or aberrant development of intellectual, motor, or social functions. "GNAI1 is a guanine nucleotide-binding protein, and mutations in this gene are known to cause neurodevelopmental disorders." (PMID 36422592, 2022). "Mutations in the GNAI1 gene, which encodes Gαi1 protein, have been recently linked to a neurodevelopmental disorder; however, it remains unknown how GNAI1 patient mutations disrupt neuronal development or function to manifest in disease." (PMID 40894620, 2025). "Here, we demonstrate that GNAI1 – the causal gene in a recently identified neurodevelopmental disorder – regulates ciliogenesis in two human cell lines, suggesting that cilia dysfunction may play a role in the pathogenesis of GNAI1 disorder." (PMID 40894620, 2025). "Recent studies identified >15 de novo mutations in the GNAI1 gene, which encodes the Gαi1 subunit of heterotrimeric G (αβγ) proteins, in individuals with a novel neurodevelopmental disorder (NDD) henceforth referred to as ‘GNAI1 disorder’." (PMID 40894620, 2025).
bacterial infections (1 paper, 2024). "GNAI1 and GNAI3 regulate cytokine responses to bacterial infections." (PMID 38881758, 2024).
immune disease (1 paper, 2020). "Studies showed that altered expression of GNAI1 was associated with the progression of inflammation and immune disease." (PMID 33149760, 2020).
kidney disease (1 paper, 2022). "However, the role of Gnai1 has never been studied in the context of kidney disease." (PMID 35678269, 2022).
GNAI1 also shares sentences with these, for which no sentence is quoted: Intellectual disability (4 papers); viral infection (4); Anxiety (3); glioblastoma (3); alcohol dependence (2); Alzheimer disease (2); autism (2); dementia (2); depression (2); encephalomyopathy (2); heart failure (2); latent infection (2); non-small cell lung carcinoma (2); Parkinson disease (2); schizophrenia (2); brain inflammation (1); breast tumor (1); epileptic seizures (1); lung carcinoma (1); mastitis (1); movement disorder (1); ocular infection (1); pituitary adenoma (1); Pruritus (1); renal cell carcinoma (1); respiratory disease (1); retinal diseases (1); serous ovarian cancer (1); thymus atrophy (1).